MYC (MYC proto-oncogene, bHLH transcription factor)
Diseases named in the same sentence as MYC in open-access papers (continued):
Sharing a sentence is not in itself a finding about the gene and the disease.
gastric cancer (continued). "Moreover, analyses of Western blot and RT-qPCR suggested that β-catenin overexpression was able to rescue KLF13-mediated down-regulation of CCND1 and MYC expressions in both gastric cancer cell lines." (PMID 36336731, 2022). "Several studies have reported that progression of GC is promoted by m6A writers, for example, METTL3-mediated m6A modification of some mRNA (HDGF, SPHK2, and MYC), which ultimately promotes gastric cancer progression, thus, exhibiting a prognostic significance." (PMID 35778697, 2022). "Moreover, research has found that MYC is a target gene of miR-148a, whose expression is decreased in gastric cancer." (PMID 36199758, 2022). "MYC has also been proven to be targeted and regulated by miR-22 to affect the progression of multiple cancers, including cervical cancer, acute myeloid leukemia, and gastric cancer." (PMID 36061355, 2022). "Furthermore, it has been reported not long ago that YWHAE silencing induced cell proliferation, invasion, and migration through the upregulation of CDC25B and MYC in gastric cancer cells in accordance with our conclusion above." (PMID 35515139, 2022). "Based on these results, we speculated that β-catenin-dependent CCND1 and MYC transcriptions appeared to be involved in KLF13-induced suppression of gastric cancer proliferation." (PMID 36336731, 2022). "We believe that miR-148a-3p participates in the progression of gastric cancer by regulating MYC." (PMID 36199758, 2022). "Moreover, the analysis from database showed the positive correlation between expression of UBAP2L and that of wnt/β-catenin downstream target genes, CCND1, AXIN2, and MYC in gastric cancer tissues, suggesting that UBAP2L activated this signaling." (PMID 34823423, 2021). "ARV-825, a BRD4 inhibitor, could effectively suppress the growth and elevate the apoptosis of gastric cancer cells via transcription downregulation of c-MYC and PLK1." (PMID 34733788, 2021). "For gastric cancer, many miRNAs have been found that control the expression of the MYC gene." (PMID 34440124, 2021). "However, the role of MYC in gastric cancer still needs to be further studied, especially its upstream regulatory mechanism." (PMID 34950208, 2021). "The trendency of MET, HK2, and MYC expression in gastric cancer tissues." (PMID 33718248, 2021). "In addition, the overexpression of the MYC gene is also found in breast, cervical, colorectal, lung, and gastric cancers and leads to cell proliferation." (PMID 33142921, 2020). "Taken together, we present evidences supporting the fact that MYC deregulation has an important role in gastric carcinogenesis and that MYC-related signatures in gastric cancer are different for each histological subtype of this disease, which is clinically relevant." (PMID 30410872, 2018). "MYC is an oncogene responsible for excessive cell growth in cancer, enabling transcriptional activation of genes involved in cell cycle regulation, metabolism, and apoptosis, and is usually overexpressed in gastric cancer (GC)." (PMID 30410872, 2018). "A pan-HER inhibitor, PF0029984, was tested in seven gastric cancer cell lines, each having one of the following abnormalities: KRAS mutation; amplification of FGFR2, MYC (V-Myc avian myelocytomatosis viral oncogene homolog) or MET (MET proto-oncogene receptor tyrosine kinase)." (PMID 29872697, 2017). "Increased MYC expression was a common finding in gastric cancer and has a role in poor prognosis." (PMID 27863420, 2016). "However, the inversely correlation between YWHAE and MYC expression seems to be important for gastric cancer cells invasion and migration." (PMID 27863420, 2016). "MYC has been described as a central driving force of the malignancy of AGS gastric cancer cells." (PMID 26760764, 2016).
gastric cancer (continued). "To investigate the potential interaction between HIF-1α, ANXA1 and MYC in primary gastric cancer, we performed a bioinformatics analysis of co-occurrence and mutual exclusivity using a RNA-seq data-set from the TCGA data-base with 265 samples of stomach adenocarcinoma (cBioPortal)." (PMID 26760764, 2016). "In addition, it is involved in regulation of MYC transcription, and it is known that certain PUF60 splice variants are overexpressed in ovarian and gastric cancer." (PMID 26497854, 2015). "Heterogeneity is common for the biomarkers HER2, CCND1, EGFR and MYC in gastric cancer and may therefore limit treatment decisions based on the analysis of a single clinical biopsy." (PMID 25649416, 2015). "MYC amplification was observed in 27 of 109 gastric cancers (24.8%)." (PMID 25649416, 2015). "In vitro studies with knocked-down MYC expression in gastric cancer cell lines demonstrated the crucial role of MYC expression in gastric tumor cell growth, survival, and the maintenance of tumor cell parameters that may contribute to malignant potential." (PMID 23717612, 2013). "Also, MYC amplification was observed in plasma and in gastric cancer cell lines established in our group." (PMID 23717612, 2013). "However, in solid human tumours like gastric cancer, MYC alterations are commonly due to gene amplification." (PMID 23717612, 2013). "In conclusion, FBXW7 and MYC mRNA may play a role in aggressive biologic behavior of gastric cancer cells and may be a useful indicator of poor prognosis." (PMID 24053468, 2013). "Additionally, our group had observed that clonal high amplification of MYC is less frequent in diffuse-type than in intestinal-type primary gastric cancer, and this was reinforced by this study." (PMID 23717612, 2013). "MYC overexpression is described as ranging from 15.6% to 100% in primary gastric cancers." (PMID 23717612, 2013). "The other component comprises several circuits involving miR-17, miR-195 and miR-497 together with NF1 (a hypoxia-activated gene), TFAP4 (another cancer gene with prognostic importance in gastric carcinoma), MYC and HNF1A, and common target genes, which can mainly be classified as cancer genes." (PMID 23987127, 2013). "In MNU-treated animals, mRNA expression and MYC copy number increased during the sequential steps of intestinal-type gastric carcinogenesis and immunoreactivity was only observed in intestinal metaplasia and gastric cancer." (PMID 21811552, 2011). "MYC amplification has been observed in gastric cancer cell lines and primary stomach tumors." (PMID 21811552, 2011). "Thus, the over-expression of Reptin observed in gastric cancer likely results from the elevated c-MYC level." (PMID 20509972, 2010). "To investigate whether this is the case in gastric cancer cells, we immunoprecipitated c-MYC-bound proteins using a c-MYC specific antibody and then performed immunoblotting analyses with an antibody against Reptin." (PMID 20509972, 2010). "In our study, we demonstrated that FMRP directly interacts with c-MYC and regulates its expression by stabilizing the protein through suppression of proteasomal degradation, thereby enhancing its activity and promoting malignant phenotypes in gastric cancer cells." (PMID 41184982, 2025). "The most frequently amplified oncogenes in gastric cancers, including MYC, ERBB2 (encoding for HER2), and CCNE1 (encoding for cyclin E), showed higher prevalence in the higher CDX2-expressing group, which was statistically significant for MYC (Fisher’s exact test p = 0.008)." (PMID 39768557, 2024). "When ANXA2 is silenced, the ability of proliferation, invasion, and migration of gastric cancer cells is weakened, but when it is overexpressed, it can promote the migration, invasion, and metastasis of esophageal cancer cells in vitro and in vivo by activating the MYC-HIF1a-VEGF cascade pathway." (PMID 35280928, 2021).
gastric cancer (continued). "In this study, we identified genes differentially expressed with a downregulated profile in gastric cancer (GC) cell lines with silenced MYC." (PMID 33351778, 2020). "Furthermore, MYC is a candidate target for new therapies against gastric cancer." (PMID 24053468, 2013). "For example, the transcription factor MYC activates LINC00346 expression by binding to promoter regions, and elevated LINC00346 expression promotes gastric cancer progression." (PMID 40416600, 2025). "Knockdown of FMR1 suppressed gastric cancer cell proliferation, migration, and invasion, while mechanistic studies indicated that FMR1 positively regulates c-MYC expression to drive these phenotypes." (PMID 41184982, 2025). "Hsa_circ_0089547 can bind to miR-449c-5p, which targets MYC, and the upregulated MYC expression enhances its combination with the NOTCH1 promoter, thereby facilitating the transcription of NOTCH1 in gastric cancer." (PMID 39452835, 2024). "In gastric cancer PDCs, we confirmed that BET inhibitors suppressed c-MYC expression in parental and DTP cells, whereas ALDH1A3 expression and cell survival were more preferentially suppressed in DTP cells than in parental cells." (PMID 38669046, 2024). "In gastric cancer, BRD4 triggers c-MYC activation, leading to enhanced cell proliferation and reduced apoptosis." (PMID 39430761, 2024). "In keeping with the capacity of the FGF/FGFR system to regulate MYC at the transcriptional level, FGFR blockade with the pan-FGFR inhibitor BGJ398 was proved to suppress MYC transcription in KKLS gastric cancer cell line." (PMID 39482742, 2024). "It plays an important role in gastric cancer progression and development by regulating the expression of cyclin B1 and B2 (CCNB1, CCNB2) and c-MYC." (PMID 37667288, 2023). "Mechanistically, METTL3‐mediated m6A modification on the proto‐oncogene c‐Myc transcript resulted in increased MYC expression and gastric cancer progression." (PMID 35560957, 2023). "Previous studies reported that MYC which located on chr8p24.21 locus (amplified in ITGB1 high subgroup), can promote malignant progression of gastric cancer cells." (PMID 37007126, 2023). "Moreover, a recent study highlighted that HBx might increase the MYC expression level by inducing the methyltransferase-like protein 3 (METTL3)-mediated N6-methyladenosine (m6A) modification of MYC mRNA, which promoted gastric cancer onset and progression in preclinical analysis." (PMID 36936956, 2023). "For example, in human gastric cancer, up-regulation of METTL3 can promote tumor angiogenesis, glycolysis, and target MYC pathway, thus serving as a potential prognostic biomarker and therapeutic target for this malignancy." (PMID 35794583, 2022). "In gastric cancer, OCT4 and MYC can bind to the promoter region of miR-9 to trigger its transcription." (PMID 35033084, 2022). "For example, METTL3 regulates SOX2 mRNA in glioma stem cell maintenance and colorectal tumor progression, LEF1 in osteosarcoma progression, AFF4/NF-kB/MYC in bladder cancer, and SPHK2 in gastric cancer." (PMID 36183833, 2022). "Thousands of up- and downregulated genes were identified by RNA-seq analysis, among which MYC and PLK1 were confirmed as downregulated makers after treatment with ARV-825 in gastric cancer cells." (PMID 34733788, 2021). "The findings demonstrated that inhibiting BRD4 by ARV-825 led to an expression reduction in MYC and PLK1 at mRNA and protein levels in gastric cancer cells." (PMID 34733788, 2021). "For example, in gastric cancer cells, circ-NOTCH1 RNA is involved in the regulation of MYC gene expression." (PMID 34440124, 2021). "We found that GCA shares some common oncogene focal amplifications with both gastric cancer and esophageal cancer including CCNE1, EGFR, and MYC." (PMID 34764264, 2021). "ARV-825 induced degradation of BRD4, BRD2, BRD3, c-MYC, and polo-like kinase 1 (PLK1) proteins in four gastric cancer cell lines." (PMID 34733788, 2021).
gastric cancer (continued). "In a recent study, it was reported that IL-8 activates mTOR and increases endogenous c-MYC production, thereby inducing PDL1 expression in gastric cancer." (PMID 32615949, 2020). "Interaction of IGF2BP1 with lncRNA GHET1 in gastric cancer and THOR in renal and skin cancer increased MYC mRNA and protein levels." (PMID 30451365, 2019). "c-MYC and CCND1 are downstream target genes of Wnt signaling, which suggests that EphA2 overexpression indeed enhances Wnt signaling in gastric cancer." (PMID 30451837, 2018). "In this study, we used next-generation sequencing based in semiconductors, as well as RNA-Seq, to quantify the transcripts and its isoforms in three gastric cancer cell lines, ACP02, ACP03, and AGP01, before and after MYC-silencing using siRNA." (PMID 30410872, 2018). "We first screened a panel of gastric cancer cell lines for their sensitivity to CDDP and correlation with protein expression of AURKA, p‐eIF4E, eIF4E, c‐MYC, and HDM2." (PMID 28417568, 2017). "Collectively, our new findings in this report add a significant novel perspective by showing that activation of AURKA–eIF4E axis is required for the induction of c‐MYC and HDM2 protein levels and CDDP resistance in gastric cancer cells." (PMID 28417568, 2017). "The results of western blot showed that the expression of CD44, SALL4, c-MYC, Oct4, Nanog, and Sox2 proteins also increased in 1 μM and 10 μM DIM-treated gastric cancer cells." (PMID 26918831, 2016). "In gastric cancer cell lines, YWHAE was able to inhibit the cell proliferation, invasion and migration through the reduction of MYC and CDC25B expression." (PMID 27863420, 2016). "For this purpose, we selected 4 genes (HER2, CCND1, MYC and EGFR) with established relevance for gastric cancer, which were previously reported to be amplified." (PMID 25649416, 2015). "In addition, MYC mRNA expression and protein immunoreactivity, as well as several molecular mechanisms previously related to its deregulation as copy number variation (CNV), mutation, and DNA methylation, were analyzed in the same set of gastric cancer samples." (PMID 23717612, 2013). "Prominent validated targets include CDK6, MYC, CCNE2, MET and GMNN and we furthermore validated the regulation of HDAC1 and SIRT1 also in gastric cancer cells." (PMID 21418558, 2011). "On the 940th day, the animal developed intestinal-type gastric cancer and had 46% of cells with 3 or more MYC copies, including 5% of cells with high amplification as determined by FISH and 3 MYC copies by qRT-PCR." (PMID 21811552, 2011). "In gastric cancer samples induced by MNU, almost 50% of cells presented MYC amplification, including 5% of cells with MYC high amplification." (PMID 21811552, 2011). "This clinical observation was supported by mechanistic studies in gastric cancer cell lines, tumor organoids, and xenograft models, demonstrating that sildenafil suppresses tumor growth by inhibiting PDE5, destabilizing c-MYC, and downregulating IL-6/JAK/STAT3 signaling." (PMID 41450924, 2025). "Additionally, AFP acts as a co-chaperone of heat shock protein 90 (HSP90), stabilizing oncoproteins c-MYC and c-MET, thereby facilitating tumor progression in liver and gastric cancers." (PMID 40485723, 2025). "Similar to hsa_circ_0003611, circ-hnRNPU binds with non-POU domain containing octamer binding (NONO) protein to decrease MYC mRNA stability in gastric cancer cells." (PMID 41318550, 2025). "In conclusion, this study reveals the oncogenic role of FMR1 in gastric cancer and demonstrates that it promotes cell proliferation, migration, and invasion via the c-MYC pathway, providing new insights into FMR1 as a potential therapeutic target for gastric cancer." (PMID 41184982, 2025).
gastric cancer (continued). "Although we demonstrated that CBX4 activates β-catenin signaling and its transcriptional activity, we did not identify or validate the specific downstream target genes (e.g., c-MYC, CCND1, AXIN2) responsible for mediating the oncogenic effects of CBX4 in gastric cancer." (PMID 41502529, 2025). "It is important to note that other lncRNAs, such as gastric carcinoma high expressed transcript 1 (lncRNA GHET1), were found to enhance the interaction between MYC mRNA and IGF2BP1, thus increasing MYC stability; however, a direct contribution to MYC’s metabolic function was not confirmed." (PMID 40126351, 2025). "In gastric cancer cells, single stranded interacting protein 1 (RBMS1) was discovered to activate the JAK2/STAT3 downstream signaling pathway after binding to the transcription factor MYC, subsequently increasing cancer migration and invasion." (PMID 38182570, 2024). "MYC directs the transcription of MCL-1 directly in gastric cancer cells; however, we did not observe a transcriptional regulation of MCL-1 by MYC." (PMID 38918775, 2024). "The overexpression of c-MYC in turn promotes the expression of LOC101929709 and LIN28B and forms a positive feedback loop that promotes the proliferation, migration and glycolysis of gastric cancer." (PMID 37582735, 2023). "For example, in gastric cancer, m6A reader IGF2BP1 upregulated in gastric cancer tissue and acted as a predictor of poor prognosis for gastric cancer patients and IGF2BP1 directly interacts with c-MYC mRNA via m6A-dependent manner to stabilize its stability." (PMID 36691477, 2023). "In gastric cancer, FOXA2-mediated FTO stabilizes MYC mRNA by reducing m6A methylation of MYC." (PMID 37932821, 2023). "Our assay results discovered that the mRNA levels of c-MYC was no markedly change in knockdown HECTD3 gastric cancer cells." (PMID 35397617, 2022). "To further demonstrate this speculation, we exogenically overexpressed β-catenin in gastric cancer cells transfected with KLF13 plasmid and analyzed expressions of CCDN1 and MYC, along with viability of cell proliferation." (PMID 36336731, 2022). "Furthermore, proteasome inhibitor MG132 was added to gastric cancer cells in knockdown HECTD3 cells, and the experimental data displayed that the expression of c-MYC was partially restored." (PMID 35397617, 2022). "ARV-825 reduced MYC and PLK1 expression in gastric cancer cells." (PMID 34733788, 2021). "In gastric cancer cell lines, YWHAE expression is significantly upregulated, and can inhibit cell proliferation, invasion, and migration by reducing the expression of MYC and CDC25B; whereas MYC induces cell proliferation, invasion, and migration by enhancing CDC25B, and reducing YWHAE expression." (PMID 34107979, 2021). "Subsequently, 2,4-diamino-quinazoline (2,4-DAQ), a selective inhibitor of Lef1, was identified to suppress the expression of Wnt/β-catenin target genes such as AXIN2, MYC and LGR5 and result in the suppression of gastric cancer cell growth through the apoptotic pathway." (PMID 32824603, 2020). "In addition to being repressed by MYC, miR‐34a is also repressed by HOTAIR upon interaction with EZH2, thereby promoting metastasis in gastric cancer cells." (PMID 30451365, 2019). "However, in several solid tumors, i.e. oral and gastric cancer, miR-494-3p acts as an anti-oncogene by targeting HOXA10 and c-MYC respectively." (PMID 28533480, 2017). "For this, we analyzed the YWHAE, CDC25B, and MYC expression in YWHA-silenced, CDC25B-silenced, and MYC-silenced gastric cancer cell lines, as well as in gastric cancer and non-neoplastic gastric samples." (PMID 27863420, 2016). "MYC-dependent regulation and prognostic role of CIP2A is reported in gastric cancer." (PMID 25015035, 2014).